TNF (tumor necrosis factor)
Diseases named in the same sentence as TNF in open-access papers (continued):
Sharing a sentence is not in itself a finding about the gene and the disease.
infection (continued). "Interleukin 12 (IL-12p70) and interferon γ (IFNγ) increased in blood during early infection; acute infection was marked by elevated circulating natural killer (NK) cells, neutrophils, and B cells, as well as increased tumor necrosis factor (TNF) and IL-10." (PMID 33021470, 2020). "Its receptors are widely expressed and TNF-α plays a key role in immunological defense processes such as inducing fever, inhibiting viral replication during infections, and leading to a permanent growth arrest in cancer." (PMID 32574268, 2020). "Following infection with Escherichia coli, cytokine expression of IL-1β, IL-6, TNF-α, and IL-10 in the intestinal mucosa significantly increases, resulting in piglets having greater villous atrophy and intestinal morphology disruption." (PMID 32547405, 2020). "Specifically, total lung FDG activity (i.e., greater than 920 cumulative-SUV) and/or the presence of an extrapulmonary site of infection observed by PET CT prior to TNF neutralization predicted reactivation with 92% sensitivity and specificity." (PMID 32730321, 2020). "H37Rv infection induced much less secretion of TNF-α at 4 h post-infection compared to the H37RvΔ1768 group in WT RAW264.7 cells (****p < 0.0001) and BMDMs (****p < 0.0001)." (PMID 32457723, 2020). "The lung homogenates of WT and AhR−/− mice were collected after 96 h, 2 and 10 weeks of infection and used to evaluate the presence of cytokines (IL-12, TNF-α, IL-1β, IL-6, IL-23, IL-2, IFN-γ, IL-4, IL-17, IL-22, TGF-β, IL-10, IL-27, and IL-35)." (PMID 32647342, 2020). "It was observed that after the infection with H. pylori, secretion of TNF-α, IL-6 and IL-8 increased considerably in AGS cells compared to basal levels." (PMID 32230910, 2020). "The delivery of exosomes recovered from the airways of influenza virus-infected mice resulted in the production of IL-6, MCP-1 and TNF, which was a very similar inflammatory profile to that observed following direct infection with influenza virus." (PMID 32477358, 2020). "IE1cc172-176 expression resulted in significantly reduced induction of transcripts from the IFNB1, IFNL1, CCL5 and TNF genes relative to the wild-type protein following infection." (PMID 32365141, 2020). "Especially noteworthy pathways in the early phase (2 hpi) of infection included Rac1, TNFα signaling via NFκB and G_α signaling events." (PMID 31906849, 2020). "Second, tiotropium has been shown to inhibit the TNF- and/or NFκB-signaling pathways, which were the most significantly upregulated pathways upon the infection of SARS-CoV-2 in NHBE cells." (PMID 32698440, 2020). "In infection-induced preterm birth, the number of macrophages is increased in the decidua, and macrophages secrete proinflammatory cytokines such as TNF-α and IL-1β." (PMID 33036475, 2020). "Infection of Syrian hamsters with either Ad14 or Ad14p1 induced expression of IL-1β and TNF-α at day 1 post infection." (PMID 32486177, 2020). "Susceptible C57BL/10 mice showed high levels of TGF-β mRNA in the footpad early in infection and high levels of proinflammatory cytokines mRNA (IL-12, TNF-α, and IFN-γ) and iNOS in the late phase of the infection." (PMID 32983013, 2020). "The other top enrichment pathways were mainly involved in inflammatory response, including TNF signaling pathway and some viral-like pathogens infection signaling pathways, which were consistent with the results of GO enrichment analysis." (PMID 33363569, 2020). "There was a statistically significant difference noted in TNF-α, IL-1β and IL-6 mRNA expression at day 3 and day 7 compared to day 1 post-infection." (PMID 32391391, 2020). "ETEC K88 treatment for 6 h till 24 h resulted in the increased levels of IL-1β and IL-8 (P < 0.05 or P < 0.01) whereas 3 h till 24 h infection induced a significant augmentation of TNF-α." (PMID 32774852, 2020). "TNF is a potent pro-inflammatory cytokine released in response to trauma or infection, and is among the most abundant early mediators in inflamed tissues." (PMID 33166339, 2020).
infection (continued). "In this case, local production of TNFα with subsequent induction of different SOCS members probably can mediate GH resistance commonly observed in the carp liver after infection with microbes/exposure to endotoxin." (PMID 32082258, 2020). "An important aspect of the host defense response is the secretion of proinflammatory cytokines like tumor necrosis factor (TNF), interleukin-6 (IL-6), and IL-1 that facilitate immune cell recruitment to the site of infection." (PMID 32229615, 2020). "In response to infection, DPSCs adopted a proinflammatory profile by increasing the secretion of IL-8, lL-1β, and TNF-α, strengthening the establishment of the dental pulp inflammation." (PMID 32984312, 2020). "Our results showed in the cerebellum a significant increase in the expression of TNFα and IFNγ from day 1 and for IL-12 from day 14 post-infection." (PMID 33322180, 2020). "It was found that the expressions of IFN-α and TNF-α significantly decreased 4 h after infection, but IL-12 gene increased significantly (P < 0.01)." (PMID 32133381, 2020). "Based on these data, IL-6, IL-1β, and TNF-α elevation during fetal infection stimulates LRG expression in fetal hepatocytes to increase the umbilical cord serum LRG levels." (PMID 33211747, 2020). "These heterogeneous TNF-α+ cell clusters have potential implications for the identification of correlates of infection and of protection, which are urgently needed in TB." (PMID 32117257, 2020). "TNF-α is an essential component of the host immune response to infection and is responsible for the release of other pro- and anti-inflammatory mediators." (PMID 32015566, 2020). "In a model using murine embryonic derived, self-renewing alveolar lung macrophages, a dramatically enhanced and earlier cytokine production after infection with vital in comparison to heat-killed MTB bacteria was observed for TNFα, IL-1α, IL-1β, and IL-10." (PMID 32033104, 2020). "By day 4 post-infection, the expression of IL-10, TNF-α, and IFN-γ remained unchanged in comparison to day 2 post-infection." (PMID 33260977, 2020). "The elevated levels of the IL-6 and TNF-α induced by infection were significantly decreased by more than 70% after the treatment with EH." (PMID 32528422, 2020). "Data emerging from China have demonstrated that in almost all cases of severe infection, high levels of IL-6 and many other pro-inflammatory cytokines (predominantly downstream of NF-kB) and TNFα were detected." (PMID 32797326, 2020). "Following infection, delayed and decreased recruitment of Fo B cell-producing IgA+, IgG+, and IgM+ were observed at week 3 after infection in the TNF-/- mice compared with the TNFf/f and BTNF-/- mice." (PMID 32742607, 2020). "Tumor necrosis factor alpha (TNF-α) secretion is elevated as a consequence of bacterial-mediated cAMP signaling subversion during early infection." (PMID 32269568, 2020). "Further, our study findings indicate that CPLE treatment modulates the infection induced cytokine levels of TNFα, IFNγ, IL6 and IL4." (PMID 32074143, 2020). "The early TGF-β burst in 17XL infected mice correlated with diminished early production of the pro-inflammatory cytokines IFN-γ and TNF-α, relative to 17XNL infections." (PMID 32043415, 2020). "This leads to the production of proinflammatory cytokines, such as tumor necrosis factor alpha (TNF-α) and IL-1β, which act in concert with the chemokines Cxcl1 and Cxcl2 to attract neutrophils to airway spaces and to other infection sites." (PMID 32209688, 2020). "During infection, macrophages are one of the main sources for elevated TNF-α levels that have already been described to lower mRNA levels of SP-A." (PMID 32316261, 2020). "Next, both WT and RAW264.7 cells that stably express TNF-α (RAW264.7-TNF-α cells) were infected with H37Rv or H37RvΔ1768 using the mixed infection experiments." (PMID 32457723, 2020).
infection (continued). "The release of chemokines can also stimulate the expression of inflammatory cytokines, such as IL-1, IL-6, and TNF-α, which can repair infection or tissue damage." (PMID 32215271, 2020). "IL-10 and TNF-α production increased in splenocytes of the L.major infected groups at 90 days post-infection." (PMID 32779429, 2020). "Classic proinflammatory cytokine genes including IL-1β and TNFα play a key role in the regulation of the inflammatory process at the early stages of infection in fish, providing the first line of host defense." (PMID 32260212, 2020). "WT levels of TNF-α, IL-1, and IL-6 increased robustly in WT pups following infection, while TNF-α and IL-6 expression was significantly reduced in IL-27Rα−/− pups." (PMID 31818960, 2020). "Sixteen hours post-infection, the frequencies of IL-6- and TNF-α-positive cells correlated with the dose of the virus." (PMID 33261178, 2020). "The present study also showed a significant up-regulation in the expression of IL-1β and TNF-α mRNA following infection with L. major compared with the control group." (PMID 33252120, 2020). "After 96 h, 2 and 10 weeks of infection lung leukocytes were obtained from infected AhR−/− and WT mice and analyzed by flow cytometry for the presence of intracellular cytokines (IL-12, TNF-α, IL-1β, IL-6, TGF-β and IL-10) in CD11c+ gated cells." (PMID 32647342, 2020). "Functionally, our data suggests that infection alters TNF-α, IFN-γ, and CD107a expression in stimulated CD49a+ NK cells." (PMID 32849583, 2020). "Apart from this, the L. donovani-infected WSX-1−/− mice display higher serum levels of IFN-γ and TNF-α on day 15 post-infection, more elevated serum IL-12 levels on day 30 post-infection compared with WSX-1+/+ mice." (PMID 32849534, 2020). "Other pro inflammatory cytokines, IL-1β and TNF-α were similarly increased in the colon after infection of Camp+/+ and Camp−/- mice." (PMID 32658599, 2020). "Several human VL studies have demonstrated elevated serum levels of IL-4, IL-6, IL-10, IL-12, IL-13, IFN-g, and TNF-a in active disease compared to asymptomatic infection." (PMID 32321156, 2020). "TNF-α released from activated mast cells recruits dendritic cells to sites of infection, which then traffic to draining lymph nodes where antigen presentation takes place." (PMID 33352850, 2020). "The results showed that the expression of antiviral genes (e.g., PKR, OAS1, and Mx2) and inflammatory cytokines (e.g., IFN-α and TNF-α) were significantly reduced within 0–4 h post-infection (P < 0.05)." (PMID 32133381, 2020). "Given that macrophages are the primary targets for various species of intracellular pathogens, the following section discusses the importance of TNF on macrophage activation during such infections." (PMID 32760383, 2020). "On day 1 post-infection, the mice were euthanized, and serum TNF-α production and bacterial burden in different organs were measured." (PMID 32457723, 2020). "The soluble variable surface glycoproteins (VSGs), shed by live trypanosomes are thought to be the major TNF-α inducers, and an increasing TNF-α concentration has been linked to a failing immune system and uncontrolled infection." (PMID 32059486, 2020). "The levels of differentially expressed IFN-γ and TNF-α in the CD4+T cells dropped down in severe cases as compared to milder infections of SARS-CoV-2." (PMID 33262955, 2020). "The concentrations of TNF-α were significantly higher in lung homogenates from mice infected with ST5 than non-ST5 infections (P = .01)." (PMID 32196550, 2020). "In the study, after infection, the levels of TNF-α, IL-6, and IL-1β in obese mice increased for a short time, and then decreased, which is conducive to reducing the inflammatory immune damage of the spleen and promoting the repair effect." (PMID 32104715, 2020). "Compared to WT animals, both TNF-α and IL-1β increased in the lungs of Il22−/− mice at the 7th day of infection, correlating with increased lung inflammation at the same time point." (PMID 32517114, 2020).
infection (continued). "NETosis does not only occur during infection, but is also initiated by proinflammatory cytokines such as IL-8, TNF-α, platelet-activating factor (PAF), and GM-CSF, as well as other stimulants such as LPS, PMA and complement factor 5a (C5a)." (PMID 32391007, 2020). "TNF-α secretion was exacerbated in a statistically significant manner in oleic acid derived foam cells at 24 and 48 h post-infection." (PMID 32754123, 2020). "Tumor necrosis factor (TNF) induces antigen-specific CD4+ cells that produce IFN-γ early during an infection." (PMID 33520738, 2020). "Further reinforcing this concept, targeting TNF-α in experimental CD reduces mechanical allodynia during the first week after infection." (PMID 33574810, 2020). "The TNF-α concentrations in lung homogenates from mice infected with this isolate were significantly higher than for infections with any other isolate of any lineage (P < .001)." (PMID 32196550, 2020). "Both miR-23a-3p and miR-23a-5p were shown to be inhibited following infection with Aeromonas hydrophila in grass carp fish, repressing TNF-α/IFN/IL-8 and promoting caspase-3/7 by targeting CiGadd45ab." (PMID 33202583, 2020). "After exposure to LPS, which mimicked the situation of a low-grade infection in addition to the presence of wear particles, TNFα secretion increased over time in both NP groups." (PMID 33343230, 2020). "Although the production of both cytokines in IFNAR-blocked BMMCs was lower than that of IFNAR−/− cells, it was still significantly higher than IFNAR-intact cells at 20 h post-infection (9.30% ± 0.79% for IL-6 and 14.75% ± 1.20% for TNF-α)." (PMID 33261178, 2020). "Various infection factors stimulate macrophages and neutrophils to produce IL-6, TNF-α, and other pro-inflammatory transmitters." (PMID 32625095, 2020). "infection, inhibiting important mediators of intracellular clearance of the parasite, such as NO, ROS, and TNF." (PMID 32692767, 2020). "IL‐1β and TNFα are two major pro‐inflammatory cytokines generated in response to infection and contribute to tissue injury during disease." (PMID 31520551, 2020). "The result detected by ELISA in mice showed that the levels of TNF-α and IL-1β were increased in the LPS-treated group compared to the control group before infection." (PMID 33232366, 2020). "CMV replication and infection require a complex interplay between an innate cytokine (TNF), cell autonomous mediator of extrinsic death (CASP8), and vICA-dependent subversion of the host inflammatory signaling." (PMID 33126536, 2020). "During infection, microglial cells are a major source of inflammatory cytokines, including IL-1β, IL-6-α, and TNF-α." (PMID 33251159, 2020). "Downregulation of proinflammatory cytokines such as tumor necrosis factor α (TNF‐α) and upregulation of anti‐inflammatory cytokines such interleukin‐10 also take place during infection." (PMID 32638533, 2020). "TNF-α was shown to appear already 4 h after infection, reaching the peak at 12 h and persisting until 20 h after infection." (PMID 33028339, 2020). "As expected, elevated concentrations of proinflammatory cytokines were observed during the acute phase of infection in the severe group, including IL-1α, IL-6, IL-8, IL-16, and TNF-α." (PMID 32990499, 2020). "Recent study demonstrated that LPS promoted the production of IL-1β and TNF-α in response to infection mediated by a mechanism for A2AR targeting in microglia." (PMID 32028987, 2020). "Infection triggers heavy cellular immune reactions in fish, with elevated level of TNF-alpha, IL-1beta, IL-6, and IgM." (PMID 33003479, 2020). "Compared with the CK group, IL-6, IL-1β, TNF-α and IL-17 all increased in the MC group under the infection of E. coli O157, while the GOS group reversed this increase under intervention." (PMID 33233359, 2020). "Other studies on the influence of TNF-alpha inhibitors on infection rates comes to different conclusions." (PMID 32600315, 2020).
infection (continued). "This concentration can increase rapidly, up to 2–5 times, during acute phases of inflammation and infection following cytokine (interleukins 1 and 6) and tumor necrosis factor (TNFα) activation." (PMID 32098273, 2020). "The difference is that, on day 0 post-infection, intraperitoneal injection of CoA can obviously induce the expressions of TNF-α, IL-1β, IL-6, and IFN-γ in the lungs, but oral administration of valine only stimulates IFN-γ." (PMID 32345342, 2020). "Daily treatment with artesunate, started two weeks after the infection, was able to significantly reduce IL-1β, IL-6, and TNF-α levels in paw tissue." (PMID 32230725, 2020). "Regarding JNK, the hypothalamus of TB animals showed an increase in the phosphorylation of this kinase on days 28 and 120 post-infection, when the highest increase in pro-inflammatory cytokines, mainly TNFα, was observed." (PMID 33322180, 2020). "Activated neutrophils produced neutrophil chemokine CXCL2 and expressed TNF-α and IL-1α in addition to very high levels of pro-IL-1β, and these proinflammatory neutrophils were major correlates of lethal infection." (PMID 33062077, 2020). "The expressions of IFNα, IFNβ, IFNλ1, Rig-I, OAS-1, MxA, IL6, IL8, and TNFα were increased at either day 1 or day 2 in WS1 post-infection or on both days." (PMID 32121148, 2020). "Second, there was a significant increasing trend in the Th1/ Th2 cytokines IL-2, TNF-a, IL-4, and IL-10 on 5–7 dpi during the middle stage of infection." (PMID 33180882, 2020). "We observed that the secretion of TNF-α occurs in two waves: an early secretion is detected within the first 24h of infection which significantly wanes during the following days." (PMID 32069329, 2020). "Proinflammatory IL-1β, IL-6, and tumor necrosis factor alpha (TNF-α) levels were markedly increased upon any infection compared to mock control and were higher during C. glabrata or C. parapsilosis infections." (PMID 33024045, 2020). "Infection with Fowl Adenovirus Group 4 (FAdV-4) is reported to increase the expression of IL-6, IL-8 and TNF-α and produce tissue damage in lymphoid organs, principally through apoptosis." (PMID 32674433, 2020). "This further implies that infiltrating immune cells are the likely source of pro-inflammatory cytokines such as IL-6 and TNFα reported to be elevated in patient sera later during infection." (PMID 33284849, 2020). "A modest but statistically significant release of IL-6 and TNF-α in response to rVSVΔM51 was observed at 12 h post-infection, which peaked by 16 h and declined by 20 h post-infection." (PMID 33261178, 2020). "After IVA infection, the volume density of TNFα-positive cells increased 2.3-fold compared to the healthy control and constituted 32.2% ± 4.7%, and the numerical density of lysozyme-positive cells decreased 2.3-fold and constituted 11.1 ± 0.6." (PMID 32937880, 2020). "Infection of P. zopfii GT-II induced pro-inflammatory responses in bMECs as demonstrated by upregulated mRNA expression of IL-1β, TNF-α and IL-8 (after 2 hpi)." (PMID 31959834, 2020). "At the protein level, only at 24 hpi did BCG_yrbE3A infection significantly induce a higher level of TNF-α production than the BCG_Vec strain (p < 0.01)." (PMID 32316659, 2020). "Our results suggested that the extract was able to induce significant TNF-α production in RAW 267 macrophages after infection with L. amazonensis." (PMID 32908533, 2020). "Being a pro-inflammatory cytokine, TNFα is known to be involved in the acute phase reaction during infection, inflammation and/or vaccination." (PMID 32221366, 2020). "The C. procera LP and LPPI administration in the peritoneal cavity was shown to induce TNF-α production within 4 h post-infection, due to the induction of NO, while non treated and infected animals had a delayed production of this cytokine." (PMID 33237133, 2020).